IL10 (interleukin 10)
Diseases named in the same sentence as IL10 in open-access papers (continued):
Sharing a sentence is not in itself a finding about the gene and the disease.
preeclampsia (75 papers, 2013 to 2025). Preeclampsia is a hypertensive disorder of pregnancy that is characterized by new-onset hypertension with proteinuria presenting after 20 weeks of gestation, and depending on mild or severe forms may initially present with severe headache, visual disturbances, and hyperreflexia. "This review outlines the conceptual framework underlying the role of IL-10 in the duality of normal pregnancy and preeclampsia together with HIV infection, thus highlighting its regulatory mechanisms and genetic influences." (PMID 39273381, 2024). "As early as 2011, a meta-analysis sought to investigate the role of the inflammatory factors TNF-a, IL-6, and IL-10, assessing both their serum expression levels and the presence of polymorphisms in women with preeclampsia." (PMID 38893732, 2024). "Imbalance of this cytokine has been linked to adverse events such as foetal loss weight, and an IL-10 knockout mouse model showed a link with preeclampsia, preterm birth, and foetal loss." (PMID 39495782, 2024). "Despite numerous attempts to correlate the impact of IL-10 SNPs with increased susceptibility to preeclampsia development, results remain inconsistent due to variations in selection criteria, sample size, ethnic diversity, and linkage disequilibrium." (PMID 39273381, 2024). "TNF-α increases during all pregnancy and has been related to miscarriages, fetal losses, preeclampsia, and preterm birth and is associated with IL-10 reduction." (PMID 37887854, 2023). "For illustration, a study of a preeclampsia model in rats with decreased uterine perfusion found that placental ischemia was associated with lower levels of IL-10 and endothelial cell dysfunction." (PMID 37168313, 2023). "In Pinheiro article also non-association between TNF-α (− 308 G → A), IL-6 (− 174 G → C), or IL-10 (− 1082 G → A) polymorphisms and preeclampsia was reported." (PMID 38057745, 2023). "Clinical studies have indicated that IL-10 is substantial for normal pregnancy, fertility, and fecundity, while IL-10 deficiency is associated with pregnancy loss, preterm birth or preeclampsia." (PMID 31947687, 2020). "TNF-α, IL-1β, and IL-6 are essential in early pregnancy, but, with the evolution of gestation, high TNF-α levels can promote preeclampsia and gestational diabetes mellitus, while low IL-10 levels are associated with preterm birth." (PMID 27294162, 2016). "In the present study, we investigated the association of three maternal IL-10 polymorphisms with preeclampsia." (PMID 25257050, 2014). "Emerging evidence shows that interleukin (IL)-10 gene polymorphisms can regulate its expression level and thus influence person's susceptibility to preeclampsia." (PMID 25257050, 2014). "The same problem also existed in the subgroup analysis of IL-10 -1082A/G polymorphism's association with preeclampsia stratified by continents." (PMID 25257050, 2014). "To explore the association between maternal IL-10 gene polymorphisms and preeclampsia, we performed a meta-analysis based upon 11 individual studies here." (PMID 25257050, 2014). "More studies are needed to investigate the role of geographical regions in determining the association between IL-10 -1082A/G polymorphism and preeclampsia." (PMID 25257050, 2014). "In conclusion, our meta-analysis results suggested that IL-10 -819C/T and -592C/A polymorphisms were associated with the risk of preeclampsia." (PMID 25257050, 2014). "As these two alleles were related to higher expression levels of IL-10 and IL-10 has been thought to facilitate successful pregnancy with IL-10 deficiency leading to preeclampsia, such correlations were somewhat counterintuitive." (PMID 25257050, 2014). "To address these issues, we performed a systemic review and a meta-analysis of all genetic association studies of maternal IL-10 polymorphisms related to preeclampsia to investigate the association between maternal IL-10 polymorphisms and preeclampsia." (PMID 25257050, 2014).
preeclampsia (continued). "Both the -819 C allele and the -592 C allele of IL-10 showed evident association with the risk of preeclampsia in our meta-analysis." (PMID 25257050, 2014). "The total number of the included studies was still relatively small, especially for the meta-analysis of IL-10 -819C/T and -592C/A polymorphisms' association with preeclampsia." (PMID 25257050, 2014). "Reduced production of IL-10 has been suggested to cause a proinflammatory cytokine response and thus lead to the pathogenesis of preeclampsia." (PMID 25257050, 2014). "Furthermore, CCL-20 cord blood levels were associated with preeclampsia and fetal leptin, insulin, IL-8, and IL-10 levels, suggesting its role in pregnancy complications, fetal adiposity, and inflammation." (PMID 40698658, 2025). "Furthermore, decreased IL-10 levels were associated with pregnancy losses, preeclampsia, and preterm delivery." (PMID 37744353, 2023). "In accordance, in women with preeclampsia, it has been proposed that higher levels of IL-10 could be associated with a compensatory mechanism due to an increase in pro-inflammatory cytokines." (PMID 37891883, 2023). "Overall, lower maternal serum IL-10 concentrations in the second trimester may be associated with the onset of preeclampsia, which may reflect the importance of anti-inflammatory and Treg cytokines in controlling inflammation midgestation." (PMID 33680514, 2021). "Decreased production of IL-10 is associated with pregnancy loss and increased preeclampsia." (PMID 30406179, 2018). "Of importance, among previous mouse models of preeclampsia, those which involved mice that had a maternal knock-out phenotype [e.g. eNOS(-/-), IL10(-/-), C1q(-/-)] were able to generate severe preeclampsia phenotype associated with intrauterine growth restriction." (PMID 25860260, 2015). "Our meta-analysis results indicated that IL-10 -819C/T (C versus T, OR = 1.28, 95% CI = 1.08–1.50, P = 0.003) and -592C/A (C versus A, OR = 1.28, 95% CI = 1.03–1.59, P = 0.03) polymorphisms were associated with preeclampsia." (PMID 25257050, 2014). "This systemic review may help to enhance our understanding of the role of IL-10 in the aetiology of preeclampsia and early identification of persons predisposed to preeclampsia." (PMID 25257050, 2014). "Only one study investigated the association of IL-10 -2849G/A polymorphism with preeclampsia." (PMID 25257050, 2014). "Besides, we also observed that IL-10 -1082G allele was correlated with the risk of preeclampsia in the Asia and the South American subgroups and both related meta-analysis results favoured the dominant model." (PMID 25257050, 2014). "However, further studies are essential to validate the association between IL-10 polymorphisms and the risk of preeclampsia." (PMID 25257050, 2014). "Given the great importance of IL-10 during pregnancy and the influence of its several polymorphic sites in the regulatory regions on its expression levels, several case–control studies have investigated the association between IL-10 gene polymorphisms and the risk of preeclampsia." (PMID 25257050, 2014). "Therefore, more studies are still called upon to further evaluate the association between IL-10 -1082A/G polymorphism and preeclampsia among persons from different geographical regions." (PMID 25257050, 2014). "It is possible that L. rhamnosus GG might reduce the risk of spontaneous PTD by suppressing mid‐pregnancy IL‐12 levels and late‐pregnancy IL‐10 levels and reduce the risk of preeclampsia by reducing levels of total lymphocytes, T‐cells, and IL‐12, as well as increasing IL‐10 levels." (PMID 41369322, 2025). "However, deficiencies in IL-10 have been associated with a plethora of pregnancy-related disorders, including infertility, spontaneous abortion, fetal growth restriction, preterm birth, preeclampsia, gestational hypertension and also with CVD." (PMID 37373945, 2023).
preeclampsia (continued). "In addition, the administration of transthyretin from preeclamptic serum into pregnant IL10−/− mice induced the hallmark symptoms of preeclampsia (hypertension, proteinuria, glomerular endotheliosis, fetal growth restriction [FGR]) whereas, transthyretin from control serum did not17." (PMID 28751735, 2017). "Aberrant TTR from the serum of women with preeclampsia reproduced preeclampsia-like features in pregnant IL-10–/– mice (a high-inflammation rodent model), and these were rescued by the administration of exogenous native human TTR." (PMID 40717228, 2025). "In the context of preeclampsia, studies have indicated aberrant levels of IL-10 in women with preeclampsia compared to healthy pregnancies." (PMID 39273381, 2024). "In the context of preeclampsia, there is, however, a reduction in IL-10 production, which exacerbates inflammatory responses." (PMID 39273381, 2024). "We observed an upregulation in interferon-gamma expression and a downregulation in transforming growth factor-beta-1 (TGF-β1), IL-4, and IL-10 in the placenta of patients with preeclampsia." (PMID 38894741, 2024). "Genetic variations in the IL-10 gene further modulate susceptibility to HIV infection and preeclampsia, albeit with nuanced effects across populations." (PMID 39273381, 2024). "Unravelling the dysregulation of IL-10 in pregnancy complications is vital, particularly in the heightened inflammatory condition of preeclampsia." (PMID 39273381, 2024). "During preeclampsia however, the imbalance between pro- and anti-inflammatory cytokines, including diminishing IL-10 levels, preempts an inflammatory state that promotes oxidative stress, anti-angiogenic milieu, and endothelial dysfunction." (PMID 39273381, 2024). "In contrast, we observed higher levels of the pro-inflammatory cytokine interleukin-6 (IL-6) and the anti-inflammatory cytokine interleukin-10 (IL-10) in the preeclampsia group than in the control group." (PMID 37168313, 2023). "IL-10 also plays a key role in protecting the placenta’s vasculature and reducing preeclampsia-like disease in rodents." (PMID 37747229, 2023). "We found that the growth regulated oncogene A (GROA) and interleukin-9 (IL-9) were associated with the development of pregnancy hypertension, whereas interleukin-10 (IL-10) and hepatocyte growth factor (HGF) were linked to the occurrence of preeclampsia." (PMID 38362587, 2023). "Conversely, most studies have reported decreased levels of anti-inflammatory cytokine IL-10 in preeclampsia cases." (PMID 37168313, 2023). "In addition, deficiencies in IL-4 and IL-10 cytokines have been associated with a plethora of pregnancy-related disorders, including infertility, spontaneous miscarriage, preterm birth, fetal growth restriction, pre-eclampsia, gestational hypertension, and as we have just demonstrated with CVD." (PMID 36012236, 2022). "Studies have shown a significant reduction in placental IL-10 mRNA and protein expression in women with preeclampsia compared to controls." (PMID 36303229, 2022). "In samples collected in the second trimester, IL-10 is significantly lower in women who later develop preeclampsia compared to women who remain healthy." (PMID 33680514, 2021). "Interleukin-10 (IL-10) is an anti-inflammatory cytokine which is reduced in the placenta of rats with reduced uteroplacental perfusion and in serum of women with preeclampsia." (PMID 34681861, 2021). "Another study showed significantly lower IL-10 concentrations in women with preeclampsia compared to controls in the third trimester." (PMID 33680514, 2021). "A recent review summarised how an imbalance between maternal proinflammatory cytokines and immune regulatory factors (Tregs and IL-10) is a key contributor to preeclampsia." (PMID 33680514, 2021).
preeclampsia (continued). "We show that cytokines TNF-α, IL-6, and IL-35 are elevated, and IL-10 is reduced in the sera of preterm preeclampsia cohort as compared to control preterm cohort, suggesting a role of chronic inflammation in disease pathology." (PMID 34195300, 2021). "Dysregulation of IL-10 has been widely confirmed in pregnancy complications such as preeclampsia, recurrent spontaneous abortion, and preterm birth." (PMID 33718261, 2021). "In contrast, others have detected significantly higher IL-10 concentrations in preeclampsia compared to healthy pregnant women." (PMID 33680514, 2021). "Another group utilizing IL-10 KO mice exposed to hypoxia to induce severe preeclampsia showed recombinant IL-10 restored blood pressure, proteinuria levels, and fetal weight to physiological values." (PMID 32337535, 2020). "It has been reported that exogenous IL-10 administration can prevent preeclampsia-like symptoms through regulating immune cell subsets related with adaptive response during pregnancy in mice." (PMID 31100843, 2019). "Seven alleles were significantly or marginally significantly associated with preeclampsia, which involved six genes (rs4762 in AGT, rs1800896 in IL-10, rs1800629 and rs1799724 in TNFα, rs2070744 in NOS3, rs7412 in APOE, and rs2549782 in ERAP2)." (PMID 30112393, 2018). "Transthyretin isolated from preeclamptic serum is also aggregated and can induce preeclampsia-like symptoms in pregnant IL10−/− mice." (PMID 28751735, 2017). "Future study is warranted to investigate the molecular mechanism of VD action on downregulating TNF-α and upregulating IL-10 during preeclampsia." (PMID 29225576, 2017). "In addition, IL10 deficiency could contribute to human gestational disorders in which an enhanced inflammatory milieu and altered DC cell responses are implicated, such as spontaneous abortion and preeclampsia." (PMID 28526846, 2017). "We have shown that IL-10 was significantly higher in the women with preeclampsia compared with pregnant healthy controls." (PMID 28747200, 2017). "This study demonstrates differences in IL10 levels in women with preeclampsia compared to the levels in women with a normal pregnancy outcome." (PMID 27335593, 2016). "The findings of significantly lower serum IL10 concentrations in patients with severe preeclampsia in comparison with respective concentrations in patients with moderate preeclampsia are highly important." (PMID 27335593, 2016). "The purpose of the actual study was to evaluate the relationship between formation of anti-inflammatory IL10 cytokine and several indicators of moderate and severe preeclampsia in the third trimester of pregnancy." (PMID 27335593, 2016). "This study demonstrated that there is significant alteration in the serum IL10 concentration in severe preeclampsia compared to normal pregnancy and in moderate preeclampsia group of patients." (PMID 27335593, 2016). "The purpose of the actual study was to evaluate the relationship between the formation of anti-inflammatory cytokine IL10 and several indicators of moderate and severe preeclampsia in the third trimester of pregnancy." (PMID 27335593, 2016). "While other variables predicted higher likelihood for the development of severe preeclampsia, IL10 decreased such likelihood." (PMID 27335593, 2016). "Study data demonstrated that in pregnant women with pregnancy complicated by preeclampsia, the serum concentration of anti-inflammatory IL10 is confirmed as a significant predictor of the occurrence of severe preeclampsia." (PMID 27335593, 2016). "We found that in pregnant women with preeclampsia, the increased serum concentrations of IL10 predicted lower likelihood for the development of severe preeclampsia." (PMID 27335593, 2016). "Average serum concentrations of IL10 were 23.2 ± 40.7 pg/ml in the total group of preeclampsia patients, 45.5 ± 48.4 pg/ml in the group with moderate preeclampsia, and 0.8 ± 0.4 pg/ml in the group with severe preeclampsia." (PMID 27335593, 2016).
preeclampsia (continued). "Increased serum concentrations of IL10 (in pg/mL) reduced the likelihood of the development of severe preeclampsia by 89.6% (95% CI 0.016-0.678)." (PMID 27335593, 2016). "The ratios IL-2/IL-10 and TNF-α/IL-10 in maternal serum are higher in preeclampsia than in normal pregnancy." (PMID 26247971, 2015). "Although higher IL-10 expression levels have been proposed to provide protection against preeclampsia, further experiments are badly needed to better elucidate the underlying mechanism." (PMID 25257050, 2014). "Evidence showed that the expression levels of placental and decidual IL-10 were altered in preeclampsia patients." (PMID 25257050, 2014). "Freeman and colleagues have recently confirmed these observations and additionally reported the significant elevation of IL-6/IL-10 ratio in women who had had preeclampsia twenty years earlier, showing the persistence of the inflammation changes." (PMID 23690796, 2013). "Previous research has shown that IL-10 is downregulated in preeclampsia." (PMID 40109359, 2025). "However, Tsai suggests that macrophages in preeclampsia transform into the M2 type, with increased IL10 secretion but weakened phagocytic capacity." (PMID 39865240, 2025). "It would be anticipated to observe a less severe form, if any, of preeclampsia in individuals with elevated viral loads due to IL-10’s purported anti-inflammatory properties, which could mitigate the inflammatory milieu during gestation." (PMID 39273381, 2024). "However, in the context of preeclampsia, this regulatory function is perturbed, leading to diminished IL-10 production and exacerbation of inflammatory processes." (PMID 39273381, 2024). "However, in the comorbid presence of HIV infection and preeclampsia, IL-10 levels are downregulated, attributable to the immune-restorative effects of ART." (PMID 39273381, 2024). "After adjusting for preeclampsia, a potential confounder in preterm birth pathophysiology, our observations remained consistent, with notably reduced Flt3L and increased IL-6, IL-2 and IL-10 levels." (PMID 39627409, 2024). "Strategies aimed at restoring immune balance and targeting IL-10 pathways to mitigate excessive inflammation and promote immune tolerance could hold promise for therapeutic interventions or the prevention of preeclampsia." (PMID 39273381, 2024). "In addition to the elevated levels of pro-inflammatory cytokine IL-6, our study also found elevated levels of anti-inflammatory cytokine IL-10 in women with preeclampsia." (PMID 37168313, 2023). "Notably, we discovered that pro-inflammatory IL-6 and anti-inflammatory IL-10 levels were higher in women with preeclampsia compared to women with uncomplicated pregnancies." (PMID 37168313, 2023). "Regarding changes in the cytokine profile in preeclampsia, there is evidence that the levels of pro-inflammatory cytokines, namely TNF-α and IL-6, are increased in preeclampsia, while the concentrations of anti-inflammatory cytokines, namely IL-4 and IL-10, are decreased." (PMID 37168313, 2023). "Likewise, two other systematic reviews also identified elevated levels of TNF-α, IL-6, and IL-10 in studies on preeclampsia." (PMID 36034841, 2022). "The third trimester is the maternal proinflammatory phase, and low levels of IL-10 due to diet may induce adverse pregnancy outcomes such as miscarriage, recurrent miscarriage, preterm delivery, and preeclampsia." (PMID 36615851, 2022). "In a lipopolysaccharide-treated preeclampsia model, Tim-3 activation induced by galectin-9 could significantly upregulate IL-10 mRNA levels in dMφs." (PMID 36303229, 2022). "Overall, several studies suggest that lower IL-10 concentrations in the second trimester (14-18 weeks) may be an early predictor for the onset of preeclampsia." (PMID 33680514, 2021). "Furthermore, mean IL-10 concentrations at 14-18 weeks are also significantly lower in women who developed severe preeclampsia (21.54 pg/mL) compared to women with mild preeclampsia (14.84 pg/mL)." (PMID 33680514, 2021).